TOMM34 (translocase of outer mitochondrial membrane 34)
Description:
Plays a role in the import of cytosolically synthesized preproteins into mitochondria. Binds the mature portion of precursor proteins. Interacts with cellular components, and possesses weak ATPase activity. May be a chaperone-like protein that helps to keep newly synthesized precursors in an unfolded import compatible state.
Synonyms: URCC3; TOM34; HTOM34P
Tractability: Antibody: UniProt places it where antibodies can reach, with high confidence. PROTAC: UniProt records ubiquitination sites on it; ubiquitination databases record sites on it; its protein half-life has been measured.
Gene: Protein-coding gene on chromosome 20 (44,942,130 to 44,960,422, reverse strand). Ensembl gene ENSG00000025772.
Subcellular location: Cytoplasm; Mitochondrion outer membrane
Subcellular location (Human Protein Atlas): Cytosol; Mitochondria; Vesicles
Gene Ontology:
Molecular function: heat shock protein binding; protein binding
Biological process: protein import into mitochondrial matrix
Cellular component: cytosol; membrane; mitochondrial outer membrane; mitochondrion; nucleus; cytoplasm
Genetic constraint (gnomAD): Loss-of-function variants: 24 observed, 38.07 expected, observed/expected ratio (o/e) 0.63, 90% interval 0.46 to 0.89. The upper end of that interval is the gene's LOEUF score, 0.89, which puts it in group 3 of 6, group 1 being the genes least tolerant of losing a copy. Missense variants: 304 observed, 373.61 expected, observed/expected ratio (o/e) 0.81, 90% interval 0.74 to 0.89. Synonymous variants: 154 observed, 149.21 expected, observed/expected ratio (o/e) 1.03, 90% interval 0.9 to 1.18.
Homologues: Orthologues: chimpanzee TOMM34 (100% identical), macaque TOMM34 (97% identical), rabbit TOMM34 (90% identical), guinea pig TOMM34 (87% identical), mouse Tomm34 (87% identical), pig TOMM34 (85% identical), dog TOMM34 (83% identical), Drosophila melanogaster unc-45 (23% identical), Drosophila melanogaster Stip1 (22% identical), Caenorhabditis elegans unc-45 (21% identical), Caenorhabditis elegans sti-1 (13% identical), Drosophila melanogaster Sgt (13% identical). Paralogues in human: SPAG1 (47% identical), UNC45A (28% identical), UNC45B (28% identical), STIP1 (26% identical), RPAP3 (25% identical), TTC12 (17% identical), DNAAF4 (16% identical), TOMM70 (15% identical), TTC1 (15% identical), STUB1 (14% identical), SGTA (13% identical), SGTB (13% identical), and 6 more.
Diseases named in the same sentence as TOMM34 in open-access papers:
TOMM34 is named in the same sentence as 33 diseases in open-access papers, as found by Europe PMC text mining. Sharing a sentence is not in itself a finding about the gene and the disease. The quoted sentences say what the papers report.
breast carcinoma (5 papers, 2019 to 2023). "The imbalance of TOMM34 expression has been discovered to be associated with the growth of many cancers, such as rectal cancer, breast cancer, lung cancer, hepatic cell carcinoma." (PMID 36249820, 2022). "Recent studies showed high levels of Tomm34 expressed in colorectal cancer, hepatocellular carcinoma, bladder cancer, breast cancer epithelial ovarian cancer and colon cancer compared to their normal tissue counterparts." (PMID 34257607, 2021). "Translocase of the outer mitochondrial membrane 34 (Tomm34) is a cochaperone of both Hsp70 and Hsp90 that was found to be overexpressed in colorectal, hepatocellular, lung and breast carcinomas." (PMID 30917858, 2019). "In cancer, high levels of Tomm34 have been reported in bladder, colorectal and breast cancers compared to their normal tissue counterparts." (PMID 30917858, 2019). "TOMM34 is a cochaperone of both Hsp70 and Hsp90, which has been found to contribute to tumorigenesis and progression of hepatocellular carcinoma, colorectal cancer and breast cancer." (PMID 36845719, 2023). "Finally, cluster #8 indicated the role of metabolic alterations in colon and breast cancer, thus providing links to the observed upregulation of TOMM34 in various tumors." (PMID 36829477, 2023). "Thus, as with breast cancer patients, Tomm34 may serve as part of a panel of markers for prognostic determination in ovarian cancers." (PMID 30917858, 2019).
colorectal cancer (4 papers, 2014 to 2024). A primary or metastatic malignant neoplasm that affects the colon or rectum. "CD4+ T cells specifically induce the expression of mitochondrial TOMM34, and the role of TOMM34 in cancer cell growth suggests its potential in anti-cancer drug development or colorectal cancer diagnosis." (PMID 39185313, 2024). "A clinical trial of the peptide vaccines RNF43 and TOMM34 combined with chemotherapy for stage III colorectal cancer revealed that patients with a positive CTL response showed good 3-year relapse-free survival regardless of HLA-A*2402 status." (PMID 36845719, 2023). "As a tumour-associated protein, Tomm34 peptide vaccination is under investigation as a therapeutic option for colorectal cancer, with significant Tomm34 cytotoxic T-lymphocyte (CTL) response observed." (PMID 30917858, 2019). "In these cancers, Tomm34 promotes colorectal cancer cell growth and is a biomarker of poor outcome in early invasive breast cancer and bladder cancer." (PMID 30917858, 2019). "In addition to the ovaries and testes, TOMM34 is overexpressed in tumor tissues, such as colorectal cancer, early invasive breast cancer, bladder cancer, lung cancer and hepatocellular carcinoma." (PMID 36845719, 2023).
liver cancer (4 papers, 2021 to 2023). An epithelial or non-epithelial malignant neoplasm that arises from the liver. "Recent studies have suggested that overexpression of TOMM34, another outer membrane translocase, predicted poor prognosis in a number of cancers including liver cancer, colorectal cancer, and breast cancer." (PMID 36321555, 2022). "In liver cancer, Gboxin inhibits cancer cell ATP production and migration via disrupting the interaction between TOMM34 and ATP5B, it shows synergistic effect with Metformin in liver cancer treatment." (PMID 36778129, 2023).
colon cancer (2 papers, 2022 to 2023). "Our results revealed that TOMM34 is implicated in numerous pathways, especially the immune system, in colon cancer." (PMID 36845719, 2023). "The aim of the study was to understand the functional roles and to unearth the potential diagnostic and prognostic value of TOMM34 in colon cancer." (PMID 36845719, 2023). "We found that TOMM34 was dramatically related to 29 of 38 T-cell markers in colon cancer and associated with 18 of 38 T-cell markers in colon cancer after adjusting for tumor purity." (PMID 36845719, 2023). "Survival analysis revealed that upregulation of TOMM34 was significantly associated with poorer survival time in colon cancer." (PMID 36845719, 2023). "Moreover, the present study investigated the underlying evidence that TOMM34 regulates immune cell infiltration in colon cancer." (PMID 36845719, 2023). "Therefore, TOMM34 was remarkably associated with shorter survival in colon cancer partially via immune cell infiltration." (PMID 36845719, 2023). "This evidence confirmed that TOMM34 is associated with immune cell infiltration in colon cancer." (PMID 36845719, 2023). "Consistent with previous studies, these results confirmed that upregulation of TOMM34 expression was significantly associated with unfavorable prognosis in colon cancer and indicated that TOMM34 may serve as an oncogene by facilitating tumor progression and immunosuppression." (PMID 36845719, 2023). "However, the underlying function of TOMM34 in colon cancer remains to be illustrated." (PMID 36845719, 2023). "In the present study, we analyzed the gene expression, protein expression and gene alterations of TOMM34 in colon cancer from several comprehensive databases." (PMID 36845719, 2023). "We qualitatively analyzed the expression of TOMM34 in tumor tissues and adjacent normal tissues of 35 colon cancer patients by LC−MS/MS analysis." (PMID 36845719, 2023). "Overall, our findings revealed that TOMM34 is a candidate prognostic biomarker and promising immunotherapeutic target against colon cancer." (PMID 36845719, 2023). "In the present study, we found that TOMM34 expression was elevated in colon cancer tissues compared with normal tissues by means of integrated bioinformatics analysis." (PMID 36845719, 2023). "By using the cBioPortal database, we found that 6.7% of colon cancer patients have gene alterations in TOMM34, of which gene amplification is the most common alteration." (PMID 36845719, 2023). "The TIMER online tool was utilized to perform correlation analysis between TOMM34 expression and infiltration of six types of immune cells in colon cancer, including B cells, CD8+ T cells, CD4+ T cells, macrophages, neutrophils and dendritic cells." (PMID 36845719, 2023). "Our findings substantiated that TOMM34 is a potential prognostic biomarker and promising therapeutic target against colon cancer." (PMID 36845719, 2023). "By using the UALCAN online tool, we investigated the correlations between TOMM34 expression and clinical traits of colon cancer in the TCGA and CPTAC modules." (PMID 36845719, 2023). "Our results confirmed that high expression of TOMM34 in tumor tissue correlates with immune cell infiltration and worse prognosis in colon cancer patients." (PMID 36845719, 2023). "The overexpression of TOMM34 may be a crucial factor in the occurrence and progression of colon cancer because previous studies have also shown that TOMM34 plays an important role in tumor cell growth." (PMID 36845719, 2023). "Moreover, we conducted multi-GSEA to further investigate the molecular mechanisms of TOMM34 in colon cancer." (PMID 36845719, 2023). "TOMM34 may serve as a potential prognostic biomarker for colon cancer diagnosis and prognosis prediction." (PMID 36845719, 2023). "Furthermore, survival analysis showed that colon cancer patients with high TOMM34 expression exhibited a significantly poorer prognosis." (PMID 36845719, 2023).
colon cancer (continued). "The present study indicated that TOMM34 could serve as a potential immunotherapeutic target against colon cancer, especially in patients with advanced-stage disease or metastasis." (PMID 36845719, 2023). "In particular, overexpression of TOMM34 was observed in colon cancer compared with normal tissues, suggesting that TOMM34 may play a crucial role in the pathogenesis of colon cancer." (PMID 36845719, 2023). "Therefore, our study will provide insights into not only the correlation between TOMM34 and colon cancer but also the mechanism of immunotherapy." (PMID 36845719, 2023). "Additionally, we employed the TIMER database to evaluate the relationship between TOMM34 expression and distinct immune signatures in colon cancer for a comprehensive understanding of TOMM34 crosstalk with the immune response." (PMID 36845719, 2023). "A study showed that TOMM34 expression was elevated in the majority of human colon cancer samples, and the siRNA-TOMM34 approach effectively suppressed gene expression and significantly inhibited cell growth in colon cancer HCT116 cells." (PMID 35610288, 2022). "TOMM34 expression was positively associated with the infiltration of CD4+ T cells and was not correlated with macrophages in colon cancer." (PMID 36845719, 2023). "However, the correlation between TOMM34 and immune cell infiltration in colon cancer has not been investigated." (PMID 36845719, 2023).
oral squamous cell carcinoma (2 papers, 2021 to 2023). "Recently, it was shown that TOMM34 knockdown in cell line models of oral squamous cell carcinoma leads to impaired growth and migration of cancer cells, as well as damage to mitochondria and increase in intracellular reactive oxygen species." (PMID 36829477, 2023). "This study aimed to investigate expression of Tomm34 and its correlations with clinicopathology in oral squamous cell carcinoma (OSCC)." (PMID 34257607, 2021). "This may give clues to TOMM34 complex and possibly contextual effects on tumorigenesis, which is confirmed by the experimental fact that TOMM34 increases the activity of ERK1/2 and MEK1/2 in HPV-positive oral squamous cell carcinoma cells but not in HPV-negative." (PMID 36829477, 2023).
bladder urothelial carcinoma (1 paper, 2023). "A recent study indicated that overexpression of TOMM34 was remarkably related to high stage, muscle invasion, high grade and shorter survival in urothelial carcinoma of the bladder." (PMID 36845719, 2023).
liver fibrosis (1 paper, 2022). "The immunohistochemistry staining and qRT-PCR assay results also showed that ETV did not change TOMM34 protein and mRNA production in the liver tissues of CCl4-induced liver fibrosis HBV-Tg mice, but FZHY+ETV could markedly increase the production of TOMM34 protein and mRNA." (PMID 36249820, 2022).
metastatic colorectal cancer (1 paper, 2021). "A phase I clinical trial of a peptide vaccine ring finger protein 43 (RNF43) and Tomm34 combined with uracil‐tegafur (UFT)/LV for patients with metastatic colorectal cancer has been done in Japan, including the safety and immunological responsiveness of this combination therapy." (PMID 34257607, 2021).
mucinous carcinomas (1 paper, 2019). "The decreased levels of Tomm34 in type I carcinomas were particularly evident in clear cell and mucinous carcinomas." (PMID 30917858, 2019).
osteosarcoma (1 paper, 2023). A usually aggressive malignant bone-forming mesenchymal neoplasm, predominantly affecting adolescents and young adults. "Previously, it was shown that ERK/MAPK signaling is inhibited in osteosarcoma cells after TOMM34 knockdown." (PMID 36829477, 2023).
ovarian carcinoma (1 paper, 2019). A malignant neoplasm originating from the surface ovarian epithelium. "The expression of Tomm34 corresponds with the dualistic model of ovarian cancer pathogenesis where high grade, type II tumours exhibit higher expression of Tomm34 in contrast to type I tumours." (PMID 30917858, 2019). "Here, we investigated the levels of Tomm34 in ovarian cancers of mixed subtypes using immunohistochemistry." (PMID 30917858, 2019). "Our data indicate that Tomm34 is commonly expressed at high levels in epithelial ovarian cancers, except for the clear cell and mucinous subtypes." (PMID 30917858, 2019). "Our data indicate that Tomm34 is commonly expressed at high levels in human ovarian cancers, except for the MOC and CCOC subtype, where high level Tomm34 is rarely seen." (PMID 30917858, 2019). "Therefore, the aim of the current study was to investigate the expression pattern of Tomm34 in ovarian carcinomas and analyse its correlation with clinico-pathological parameters." (PMID 30917858, 2019). "The co-chaperone Tomm34 is frequently expressed in epithelial ovarian cancers." (PMID 30917858, 2019). "Although further research will be required to elucidate the mechanisms that regulate Tomm34 in ovarian and other cancers, our data imply that Tomm34 has pro-tumourigenic actions and may serve as a useful prognostic indicator and potential therapeutic target in ovarian cancers." (PMID 30917858, 2019). "Previous data have indicated that the ovary also expresses TOMM34 mRNA although its expression in ovarian cancer has not been reported." (PMID 30917858, 2019). "The expression profile of Tomm34 in ovarian cancer has not been investigated." (PMID 30917858, 2019).
cancer (18 papers, 2011 to 2025). A tumor composed of atypical neoplastic, often pleomorphic cells that invade other tissues. "A comprehensive analysis of the multiomics data revealed that TOMM34 interacts with deregulated cancer-associated pathways such as NOTCH, MAPK, and STAT3 signaling pathways." (PMID 39936995, 2025). "Such profound association with oncogenesis prompted to design a cancer vaccine that contains TOMM34-derived peptides for the treatment of colorectal cancer." (PMID 36829477, 2023). "Here, we report genes and pathways associated with TOMM34, Translocase of Outer Mitochondrial Membrane, which plays role in the mitochondrial protein import as a part of cytosolic complex together with Hsp70/Hsp90 and is upregulated in various cancers." (PMID 36829477, 2023). "However, TOMM34 has been associated with many diseases including cancer and neurodegeneration, which suggests that this gene has other functions." (PMID 36829477, 2023). "Moreover, TOMM34 deficiency rendered cancer cells more vulnerable to such metabolic stress, while overexpression of TOMM34 assisted HCC cells to survive through these metabolic stresses." (PMID 36321555, 2022). "In the dynamics of mitochondrial protein trafficking, TOMM34 forms a complex with Hsp70/90 (the Hsp70-TOMM34-Hsp90 complex) that is upregulated in many cancers." (PMID 39936995, 2025). "Expression of the mitochondria-related genes including SLBP, ARPC1A, and TOMM34 (TCGA database) were significantly higher in cancer tissues than the normal tissues." (PMID 39012280, 2024). "Concerning the association of TOMM34 to cancer, another significantly upregulated gene, TXNIP (log2FC = 2.86), has been shown to perform tumor suppressor function in several cancer cell types." (PMID 36829477, 2023). "To evaluate the role of TOMM34 in predicting immunotherapeutic benefits, we utilized The Cancer Immunome Atlas (ICIA) to assess the immune response." (PMID 36845719, 2023). "Increased expression of TOMM34 has been detected in various cancers including oral squamous cell and hepatocellular carcinoma, ovarian, colorectal, bladder, and gastric cancer." (PMID 36829477, 2023). "Collectively, these data suggested that TOMM34 is critical for cancer cell survival under diverse metabolic stresses including metformin treatment." (PMID 36321555, 2022). "The data were correlated with tumour type and clinicopathological variables and demonstrate that Tomm34 is expressed at high levels in type II carcinomas and correlates with high FIGO stage." (PMID 30917858, 2019). "TOMM34 was identified as differentially expressed between intestinal-type and diffuse-type gastric cancer, suggesting it plays a role in the distinct molecular pathways of these cancer subtypes." (PMID 39185313, 2024). "As metabolic stress is a critical barrier during cancer metastasis, and metformin‐adaptive cells exhibited a mesenchymal cell phenotype, we hypothesized that TOMM34‐mediated metabolic adaptation might promote HCC metastasis." (PMID 36321555, 2022). "Intervening such TOMM34‐mediated metabolic adaptation might hold the potential to suppress tumor metastasis and achieve better clinical outcomes for cancer patients." (PMID 36321555, 2022). "However, the mechanisms involved in TOMM34‐regulated cancer progression and drug response remain largely unclear." (PMID 36321555, 2022). "Tomm34 is not expressed in most important organs such as heart, liver, kidney and lung, which indicates that the side effects of using Tomm34 as an anti-cancer target may be minimal." (PMID 34257607, 2021). "Tomm34 was more highly expressed in type II than type I carcinomas (p < 0.0001)." (PMID 30917858, 2019). "This, together with the observed downregulation of GPX8 gene (log2FC = −2.27), which functions to combat oxidative stress, might explain the results from the previous study, where decreased proliferation and increased oxidative stress were observed for cancer cells after TOMM34 knockdown." (PMID 36829477, 2023).